RN7SKP106 (RN7SK pseudogene 106)
Gene: Miscellaneous RNA gene on chromosome 6 (141,486,141 to 141,486,412, reverse strand). Ensembl gene ENSG00000222764.
Homologues: Orthologues: chimpanzee 7SK (94% identical), guinea pig 7SK (62% identical), mouse Gm54647 (51% identical). Paralogues in human: RN7SKP255 (76% identical), RN7SKP8 (76% identical), RN7SKP180 (75% identical), RN7SKP79 (75% identical), RN7SKP9 (75% identical), RN7SKP124 (74% identical), RN7SKP237 (74% identical), RN7SKP71 (74% identical), RN7SKP133 (74% identical), RN7SKP243 (74% identical), RN7SKP78 (74% identical), 7SK (74% identical), and 284 more.